PRRT2 (proline rich transmembrane protein 2)
Diseases named in the same sentence as PRRT2 in open-access papers (continued):
Sharing a sentence is not in itself a finding about the gene and the disease.
neurological diseases (19 papers, 2014 to 2025). "The spectrum of FHM mutations even in the last decade has increased, and there are new mutations being identified, which can cause the phenotype alongside other neurological disorders such as those associated with PRRT2 mutations." (PMID 37628876, 2023). "In this study, we investigated the clinical features and role of the underlying PRRT2 genetic mutations in 10 children with related neurological diseases." (PMID 36467477, 2022). "The position of the polymorphic glycine in PRRT2 associated with neurological disease (G305W) is underlined." (PMID 33112230, 2020). "Clinical data of 62 family members were included, comprising a cohort of 102 individuals (extended cohort) with PRRT2-associated neurological disease." (PMID 33126500, 2020). "Our study on a representative group of patients presenting with BFIS highlights the variability of phenotypic presentations associated with variants of PRRT2 and provides additional insight into the spectrum of PRRT2-related neurological disorders." (PMID 33126500, 2020). "We enrolled 10 children with PRRT2 mutation-related neurological diseases who visited the Children's Hospital affiliated with the Shanghai Jiaotong University School of Medicine/Shanghai Children's Hospital between May 2017 and February 2022." (PMID 36467477, 2022). "Proline-rich transmembrane protein 2 (PRRT2) encodes a SNARE-like motif that enables interaction with neuronal SNARE proteins; mutations in this region disrupt SNARE binding and are linked to neurological disease." (PMID 39653855, 2025). "This study aimed to summarize the clinical characteristics and gene expression analysis of neurological diseases related to the PRRT2 gene and explore the clinical characteristics, therapeutic effects, and possible pathogenic mechanisms of related diseases." (PMID 36467477, 2022). "Proline-rich transmembrane protein 2 (PRRT2) plays an important role in the central nervous system and mutations in the gene are implicated in a variety of neurological disorders." (PMID 36467477, 2022). "Summary of clinical data of 10 children with proline-rich transmembrane protein 2 (PRRT2)-related neurological disorders." (PMID 36467477, 2022). "Since the GxxxG motif is a shared feature of IFITM3 and PRRT2 and that a naturally occurring mutant G305W is predictive of neurological disease, we assessed the oligomerization capacity of WT and mutant PRRT2." (PMID 33112230, 2020). "Mutations in the proline-rich transmembrane protein 2 gene (PRRT2, NM_145239.2) have been identified to be the causes of many neurological diseases." (PMID 27172900, 2016). "The study of neurological diseases associated with impaired neurotransmission has led to the identification of cellular proteins that regulate synaptic SNARE assembly, such as proline-rich transmembrane protein 2 (PRRT2)." (PMID 39653855, 2025). "Proline rich transmembrane protein 2 (PRRT2) encodes a SNARE-like motif that enables interaction with neuronal SNARE proteins, and mutations therein disrupt SNARE binding and are linked to neurological disease." (PMID 41030966, 2024). "As we included symptomatic family members with known or putative mutations in PRRT2 in our extended cohort, estimates of phenotypic variability in this group might be more representative of PRRT-related neurological disorders." (PMID 33126500, 2020). "A reduction or no production of the PRRT2 protein might cause alterations in synaptic neurotransmitter release and/or a dysregulation of the neuronal excitability in different sides of the brain, causing different types of neurological disorders." (PMID 31801583, 2019). "However, this apparent disequilibrium might have occurred by chance since to our knowledge, no transmission disequilibrium was reported for PRRT2 mutations in other neurological diseases." (PMID 24594579, 2014).
movement disorder (9 papers, 2018 to 2025). Neurological conditions resulting in abnormal voluntary or involuntary movement, which may impact the speed, fluency, quality and ease of movement. "Homozygous PRRT2 variants in our cohort were associated with SeLIE with normal development and comorbid movement disorders." (PMID 40401013, 2025). "Neurologic comorbidities were present in 10 children with heterozygous PRRT2 variants (10/33, 30%), and movement disorders (n = 4/10, 40%) (cases 2, 13, 18, and 38) and tone abnormalities (n = 4/10, 40%) (cases 14, 15,18, and 19) were the most common comorbidities." (PMID 40401013, 2025). "All children with homozygous PRRT2 variants had SeLIE with movement disorders." (PMID 40401013, 2025). "In addition, PRRT2 pathogenic variants have been identified in other childhood-onset movement disorders and different types of seizures, suggesting that the understanding of the spectrum of PRRT2-PxMD is still evolving." (PMID 35715422, 2022). "Both our histological and biochemical experiments have shown that PRRT2 is highly expressed in cerebellar GCs, suggesting a potentially important role of cerebellum in PRRT2-related movement disorders." (PMID 29056747, 2018).
infection (5 papers, 2012 to 2020). The state of being infected such as from the introduction of a foreign agent such as serum, vaccine, antigenic substance or organism. "Infection of low-density mouse cortical neurons with the appropriate lentiviral vectors resulted in an effective silencing of PRRT2 and in the expression of the shRNA-resistant version of PRRT2 overriding the RNA interference." (PMID 27052163, 2016). "A recent study reported relatively high glutamate levels in the plasma samples of PKD patients, and an increased glutamate level in the culture medium of neurons after infection with shRNA-Prrt2 lentivirus, indicating the involvement of PRRT2 in the release of glutamate." (PMID 27449084, 2016). "We showed an increase in glutamate levels in the culture medium of neurons after infection with shRNA-Prrt2 lentivirus, suggesting that mutant PRRT2 might affect the release of glutamate." (PMID 25915028, 2015). "Infection of hippocampal neurons at MOI 2 with the appropriate lentiviral vectors resulted in an effective silencing of PRRT2 and in the expression of the shRNA-resistant version of PRRT2." (PMID 33056987, 2020).
autosomal dominant disease (2 papers, 2019 to 2021). Autosomal dominant form of disease. "HM can also be part of the phenotypic manifestations associated with PRRT2 gene mutations, but PRRT2 most likely acts as a disease-modifying gene within the context of complex polygenic rather than autosomal dominant disease." (PMID 31681150, 2019).
neurodevelopmental disorder (2 papers, 2019 to 2025). A behavioral and cognitive disorder with onset during the developmental period that involves impaired or aberrant development of intellectual, motor, or social functions. "Case 16 also has a de novo pathogenic variant in PRRT2, a regulator of neurotransmitter release associated with a variety of neurological and neurodevelopmental disorders." (PMID 40894167, 2025).
brain disorder (1 paper, 2021). A disease affecting the brain or part of the brain. "In fact, subsequent research has implicated PRRT2 in synapse functioning, which justifies the classification of PRRT2-associated conditions as “synaptopathies,” an emerging rubric of brain disorders." (PMID 33746883, 2021). "However, recent evidence implicates PRRT2 in synapse functioning, which disproves the “channel hypothesis” (although PRRT2 modulates ion channels at the presynaptic level), and justifies the classification of these conditions as synaptopathies, an emerging rubric of brain disorders." (PMID 33746883, 2021).
genetic disease (1 paper, 2023). "Among protein-coding genes located between BP4 and 5, five genes, including TAOK2 (a pLI score of 1.00), CORO1A (0.97), MAZ (0.93), PAGR1 (0.74), and PRRT2 (0.59), have a pLI value of 0.5 or more and are associated with symptoms related to 16p11.2 deficits and are implicated in genetic disease." (PMID 38203422, 2023).
PRRT2 also shares sentences with these, for which no sentence is quoted: hepatocellular carcinoma (9 papers); paroxysmal non-kinesigenic dyskinesia (7); cholangiocarcinoma (6); liver cancer (6); Chorea (5); Insulin resistance (4); Hyperglycemia (3); liver diseases (3); Obesity (3); biliary tract cancer (2); Cerebellar atrophy (2); childhood absence epilepsy (2); depression (2); fibrosarcoma (2); glioma (2); headache disorder (2); Paroxysmal exertion-induced dyskinesia (2); adenocarcinoma (1); Adult onset (1); alternating hemiplegia of childhood (1); Angelman syndrome (1); Arrhythmia (1); Atrophy (1); autoimmune disease (1); benign fibrous histiocytoma (1); biotinidase deficiency (1); bladder cancer (1); breast invasive carcinoma (1); cardiac hypertrophy (1); cardiovascular diseases (1).
A further 62 diseases each share a sentence with PRRT2 in 1 paper.